INS (insulin)
Diseases named in the same sentence as INS in open-access papers (continued):
Sharing a sentence is not in itself a finding about the gene and the disease.
Insulin resistance (continued). "T2DM or insulin resistance is characterized by high glucose level in the blood because of a decreased insulin sensitivity in metabolic tissues, leading to complications including obesity, hypertension, atherosclerosis, liver failure, and certain cancers." (PMID 35409099, 2022). "Evidence of brain insulin resistance induced by acute AP dosing can inform the early use of adjunctive insulin sensitizers for the treatment of metabolic comorbidities associated with AP treatment in severe mental illness." (PMID 36441736, 2022). "We observed that β-cell-specific insulin resistance resulted in insulin hypersecretion in the context of unchanged β-cell mass." (PMID 35136059, 2022). "After four weeks of probiotic use, a significant improvement in fasting blood sugar and insulin and insulin resistance levels was observed." (PMID 35685534, 2022). "In conclusion, SGLT2i treatment improved liver function, decreased hepatic insulin resistance, and increased hepatic insulin clearance, despite the small weight reduction." (PMID 35115614, 2022). "Insulin therapy in T1D can reduce insulin resistance and promote β-cells function by lowering blood glucose levels." (PMID 35725834, 2022). "A well-recognized mechanism of obesity-related insulin resistance is associated with the functional deficiency of IRS-1 phosphorylation, which results in abnormal insulin action." (PMID 35326098, 2022). "Brain insulin resistance has been posited to be at the cross-roads of many cognitive and metabolic disorders, and disruption of central insulin action has emerged as a possible explanatory mechanism underlying AP induced metabolic dysfunction." (PMID 36441736, 2022). "The underlying mechanism of the antidiabetic effects of these compounds include improvement in insulin secretion, decrease in insulin resistance, enhanced glycogen synthesis in the liver, and antioxidant and anti-inflammatory activities." (PMID 36437832, 2022). "Fasting blood glucose, insulin, and insulin resistance index levels in T2DM rabbits were significantly higher than those in the control group (p < 0.001)." (PMID 36741851, 2022). "In adipocytes, treatment with DDP4 induced dose-dependent decrease of insulin-stimulated Akt phosphorylation, and consequent insulin resistance, demonstrating an autocrine effect of DPP4 in these cells." (PMID 36140405, 2022). "People with IGT show higher two-hour insulin and glucose concentrations, indicative of muscle insulin resistance (MIR)." (PMID 35327447, 2022). "Putting this information together, if a fasting person has high dietary intakes of carbohydrates and fat, this results in high glucose and insulin levels (i.e., insulin resistance), increases leptin, decreases adiponectin, and increases circulating PCSK9." (PMID 35454343, 2022). "HOMA-IR is a well-established method for estimating beta cell function and insulin resistance at a steady state, in which high HOMA-IR values indicate low insulin sensitivity, such as insulin resistance." (PMID 35055664, 2022). "Serum fasting insulin levels and fasting lipid profiles were measured, and insulin resistance was calculated using HOMA-IR." (PMID 35482462, 2022). "In this late-stage of T2D, insulin administration is required, but, due to the pre-existing insulin resistance, outcomes are poor." (PMID 36291702, 2022). "Early in response to hyperglycemia and insulin resistance, β-cells can compensate by increasing secretory capacity to boost insulin production." (PMID 35204835, 2022). "HOMA-IR is a convenient and inexpensive surrogate measure of estimating insulin resistance, derived from a mathematical assessment of the balance between hepatic glucose output and insulin secretion from fasting levels of glucose and insulin." (PMID 35937831, 2022). "The objective of our study was to compare the serum cortisol, serum glucose, serum insulin, and homeostasis model assessment-insulin resistance (HOMA-IR) index between preterm and term newborns at birth." (PMID 36654578, 2022).
Insulin resistance (continued). "The role of homocysteine as a pro-oxidant is well-established, as is the role of oxidative stress in insulin resistance and disruption of insulin signalling." (PMID 36235580, 2022). "This review discusses the mutual ambiguous relationship of low-grade inflammation, insulin resistance, hyperinsulinemia and the insulin-dependent modulation of macrophage activity with a focus on adipose tissue and liver." (PMID 35955975, 2022). "The elevation of glucose in the circulation leads to insulin synthesis that, when overproduced, finally results in peripheral insulin resistance, affecting adipose and muscle mass." (PMID 36158184, 2022). "It is clear that high insulin level is needed to overcome high insulin resistance in a very early gestational period." (PMID 36654578, 2022). "The interest in the environment and insulin resistance or beta-cell dysfunction is conceivable and expected, since insulin sensitivity and beta-cell function are likely the most relevant factors in the regulation of glucose homeostasis." (PMID 36554367, 2022). "In some investigations, it has been proved that the extract of O. stamineus and its active components promoted insulin secretion, improved insulin resistance, and enhanced insulin sensitivity." (PMID 35056765, 2022). "The homeostatic model assessment (HOMA), based on fasting glucose and fasting insulin levels, was used to index insulin resistance." (PMID 35267895, 2022). "Here, we investigated the role of SFA-induced miR-183-5p in the regulation of proximal insulin signaling molecules and the development of hepatic insulin resistance." (PMID 35328400, 2022). "Insulin resistance induced by impaired insulin signaling pathway disturbs translocation of glucose transporter (GLUT)-4 that is needed for glucose uptake primarily in striated muscles and adipose tissue." (PMID 36309772, 2022). "Because PAK1 protein levels are reduced in skeletal muscle from T2D individuals, we used hPAK1-overexpressing L6-GLUT4-myc myoblasts exposed to chronic insulinemia (5 nM insulin for 12 h) as a model of insulin resistance." (PMID 35222279, 2022). "This sphingolipid, when accumulated, is known to demonstrate numerous destructive cell effects, including the development of metabolic disorders such as impairments of insulin signaling pathway and related insulin resistance." (PMID 35216351, 2022). "Concurrent with insulin resistance, the regular bursts of insulin from the pancreas become irregular." (PMID 35163806, 2022). "The partial injury of β cells combined with HFD can impair the function of insulin, resulting in insulin resistance in T2DM mice." (PMID 36016679, 2022). "In other words, when the body is in a state of insulin resistance, higher insulin concentrations are required to activate its receptors for normal physiological functions owing to reduced insulin sensitivity." (PMID 36005597, 2022). "Studies found that elevation of insulin during insulin resistance affects the lipid metabolism, and resulting in the disturbed plasma lipid level." (PMID 36185686, 2022). "Epigallocatechin gallate is an important tea polyphenol, which can improve insulin resistance by activating the 5′-adenylic acid mitogen-activated protein kinase pathway or upregulating the level of insulin signaling protein." (PMID 35422845, 2022). "One of the major characteristics of T2DM is insulin resistance, i.e., the lowered ability of peripheral tissues to respond to physiologic doses of insulin." (PMID 36479211, 2022). "For instance, research has reported an inverse correlation between dietary fiber intake and body fat accumulation, insulin resistance, fasting insulin, and glucose tolerance in PCOS women." (PMID 36558444, 2022). "PCR-array analysis showed that long-term honey intake increased the expression of genes involved in insulin sensitivity and decreased genes involved in neuroinflammation or lipogenesis, suggesting improvement of central insulin resistance." (PMID 35215406, 2022).
Insulin resistance (continued). "It is worth noting that the patients received insulin therapy, indicating that they exerted both insulin resistance and decreased insulin secretion." (PMID 35312718, 2022). "HFD-fed mice developed insulin resistance, as evidenced by their elevated fasting glucose and insulin levels." (PMID 35406688, 2022). "GTT is a common method used to evaluate glucose tolerance status that can provide information about insulin resistance and insulin secretion both directly and indirectly." (PMID 36358477, 2022). "A multilevel mixed-effects generalized linear model was performed at the contextual and individual levels with each insulin resistance marker (fasting insulin, HOMA-IR, and blood glucose levels)." (PMID 36078265, 2022). "Multiple interconnected molecular mechanisms have been identified underlying the interference of these inflammatory signals with insulin signaling, including the induction of ceramide synthesis, eventually resulting in insulin resistance." (PMID 36003642, 2022). "SOCS expression has been found to be upregulated in insulin resistance, implying that it plays a role in the feedback control of insulin signaling and the development of diabetes." (PMID 36589630, 2022). "It has been previously suggested that insulin sensitivity is one of the main contributors to metabolic flexibility; however, it is less clear if metabolic flexibility precedes or follows insulin resistance in African American women." (PMID 36232212, 2022). "T2DM is a chronic disease characterized by subclinical inflammation likely responsible for abnormal insulin secretion and peripheral insulin resistance." (PMID 35335211, 2022). "Some studies have shown that TNF-α is associated with an increased risk of developing T2D, acting through an intersection of the TNF-α and insulin signaling pathways to induce insulin resistance." (PMID 35055191, 2022). "Vitamin D receptors (VDR) are found on pancreatic islet β cells and act to increase insulin secretion, and several studies indicate that vitamin D supplementation reduced insulin resistance (IR)." (PMID 35365764, 2022). "T2DM can be attributed to insulin resistance and a corresponding failure of pancreatic islets to maintain appropriate insulin output to compensate for the decline in insulin sensitivity." (PMID 35935651, 2022). "Recent studies have shown that myo-inositol supplementation has insulin-sensitizing effects, reduces insulin resistance following pregnancy, and increases BMI." (PMID 35794663, 2022). "Six-month decreases in fasting insulin, homeostasis model assessment of insulin resistance (HOMA-IR), and waist circumference were significantly greater in the intervention than usual diet group." (PMID 36287562, 2022). "Our in silico analysis showed that, together with miR-21-5p, miR-26a-5p and miR-222-3p targeted the PTEN gene, suggesting that the PI3K-AKT insulin signaling pathway should be further explored as a potential therapeutic target for insulin resistance in PCOS." (PMID 36206272, 2022). "Serum insulin and insulin resistance measured by the HOMA-IR index were significantly lower in metformin group compared to control group." (PMID 35574481, 2022). "Reductions in CRP occurred in parallel with bodyweight loss and were positively correlated with reductions in bodyweight, waist circumference, fasting plasma glucose, fasting serum insulin, and homeostatic model assessment of insulin resistance." (PMID 36467859, 2022). "Insulin resistance (IR) is the inverse state of insulin sensitivity (IS) and the relative unresponsiveness of peripheral tissues to the effects of the hormone." (PMID 36465645, 2022). "The mice with medisobasal hypothalamic region-directed ATG7 knockdown developed systemic insulin resistance with higher level of glucose intolerance and hyperinsulinemia, suggesting that autophagy is necessary in maintaining insulin sensitivity." (PMID 35909524, 2022).
Insulin resistance (continued). "On the other hand, increased oxidative stress and inflammation can lead to insulin resistance and impair insulin secretion." (PMID 36139749, 2022). "Metformin hydrochloride tablets or insulin sensitizers such as pioglitazone can be taken orally to improve insulin resistance." (PMID 36162988, 2022). "Metabolic dysregulation promotes insulin resistance, and the pancreas is exposed to high levels of endogenous insulin, which has mitogenic and anti-apoptotic effects." (PMID 34687971, 2022). "Activation of SIRT1 inhibits the expression of intracellular uncoupling protein-1 (UCP-1), further leading to increased insulin secretion and improved insulin resistance." (PMID 35739982, 2022). "Although insulin resistance is initially compensated for by insulin hypersecretion once β-cell islet dysfunction arises, this compensatory response eventually becomes compromised, leading to the development of T2DM." (PMID 35208623, 2022). "Insulin sensitivity was evaluated by the homeostasis model assessment-estimated insulin resistance (HOMA-IR)." (PMID 36387872, 2022). "An underlying pathophysiological condition of T2D and obesity is insulin resistance (IR), a reduced biological response to insulin in peripheral tissues such as the liver, adipose tissue, and skeletal muscle." (PMID 36093112, 2022). "Gestational diabetes mellitus (GDM) is characterized by hyperglycemia, resulting from an inability of the maternal pancreas to secrete enough insulin to compensate for insulin resistance that is a normal metabolic adaptation of pregnancy." (PMID 35456307, 2022). "Increased adiposity and low-grade inflammation in adipose tissue are major features of insulin resistance where IL-1 ligands are central players in proinflammation altering insulin sensitivity." (PMID 36014927, 2022). "This metabolic derangement is characterized by insufficient insulin secretion from pancreatic β-cells to compensate for pregnancy-induced physiologic insulin resistance." (PMID 34996380, 2022). "Previous studies have indicated that high estrogen in premenopausal women improves insulin sensitivity, while in males it rather increases insulin resistance." (PMID 35782294, 2022). "The Goto-Kakizaki (GK) rat, a non-obese and spontaneous (genetic) model of T2D, exhibits alterations in β-cell response, impaired glucose-induced insulin secretion, glucose intolerance, peripheral insulin resistance and chronic inflammation." (PMID 35054496, 2022). "Glucose tolerance, insulin tolerance, insulin sensitivity, and insulin resistance index respond to the glucose metabolism ability of the mice." (PMID 36532537, 2022). "A similar trend was shown in reducing serum insulin and the homeostatic model assessment of insulin resistance index." (PMID 36670891, 2022). "Insulin resistance means that cells cannot effectively utilize insulin, which means that they cannot properly turn glucose into energy." (PMID 36498367, 2022). "The akt gene, known to be a central component in the signaling pathways activating the kinase family for assessing early stage insulin resistance, was significantly downregulated over time after insulin immersion." (PMID 35955446, 2022). "Insulin resistance is defined as a failure of target tissues to exhibit a normal response to insulin." (PMID 35739484, 2022). "In states of insulin resistance, beta-cells compensate by increasing insulin secretion to maintain glucose homeostasis." (PMID 35918636, 2022). "Plantago ovata significantly reduced HbA1c (−0.9%; −1.4 to −0.3), FBG (−32 mg/dl; −40 to −23), fasting C-peptide (as insulin sensitizer; −2.5 ng/ml; −3.22 to −1.78), and insulin resistance (−3.5; −4.6 to −2.4), and increased HDL-C (7 mg/dl; 1–13)." (PMID 35754481, 2022). "Insulin resistance is a condition in blunted response to insulin stimulation of target tissues, and it manifests as hyperglycemia and compensative hyper-insulinemia." (PMID 35624887, 2022).
Insulin resistance (continued). "In the same study, circulating DPP-4 concentration in insulin-sensitive obese patients was significantly lower than in those with insulin resistance." (PMID 35205155, 2022). "Insulin resistance (IR), defined as a reduction of the biological efficiency of insulin and insulin sensitivity in peripheral tissues, is the basis of the pathophysiology of T2DM." (PMID 36355175, 2022). "Consistent with the role for BVR-A in regulating insulin signalling, several studies have highlighted the association between impaired BVR-A and brain insulin resistance development." (PMID 35628384, 2022). "In a previous study, cells developed significant insulin resistance after 48 h of high-concentration insulin stimulation." (PMID 36296732, 2022). "Other research reports that β cell mass in subjects with obesity is assumed to increase, since plasma insulin levels in obese subjects increase to compensate for insulin resistance, a process known as hyperinsulinemia." (PMID 35198097, 2022). "The only parameter that differed between the groups was insulin levels, which were related to insulin resistance." (PMID 36079871, 2022). "Mice with α-syn pathology in the pancreas develop reduced glucose-stimulated insulin secretion and insulin resistance at the same time." (PMID 35255986, 2022). "Utilizing these technics, simply using the fasting blood glucose and insulin levels, homeostatic model assessment–insulin resistance (HOMA-IR) index and quantitative insulin sensitivity check index (QUICKI) can be calculated." (PMID 35054972, 2022). "In fact, patients with higher levels of ALA showed better insulin sensitivity, with a lower insulin resistance and lower hepatic insulin resistance." (PMID 34609622, 2022). "Insulin resistance is a condition in which the effect of insulin on target tissues is reduced despite normal or elevated levels of insulin in the blood serum." (PMID 36012251, 2022). "In our study, 35 obese patients with T2DM showed significant improvements in body weight, BMI, waist circumference, ABSI and insulin resistance, c-peptide, and insulin after receiving GB." (PMID 35277004, 2022). "Several mechanisms have been proposed linking insulin resistance to elevated blood pressure such as excess circulating insulin increasing renal sodium absorption, increased sympathetic nervous system activity, and vascular smooth muscle proliferation." (PMID 36119740, 2022). "Body mass index, serum levels of glucose, oral glucose tolerance test (OGTT), insulin, haemoglobin A1C, homeostatic model assessment of insulin resistance (HOMA IR) and irisin were evaluated." (PMID 36117331, 2022). "Insulin resistance (IR) is a common metabolic disorder in which the response of the tissues and organs to insulin is impaired, leading to poor oxidation of glucose and a reduction in glycogen synthesis." (PMID 35865388, 2022). "New-onset diabetes is considered to be characterized by impaired insulin secretion and insulin resistance." (PMID 36576596, 2022). "Female mice have been shown to be less prone to the development of diet-induced obesity and insulin resistance; males have different expression profiles of genes involved in the insulin signalling pathway and increased inflammation compared to female mice." (PMID 34338868, 2022). "In states of insulin resistance, the protective role of insulin regarding Aβ accumulation is diminished, and, in turn, Aβ deposits downregulate the action of insulin." (PMID 35615716, 2022). "Our data demonstrated that insulin-resistant cells had significantly impaired glucose uptake and that the use of RB increased sugar uptake and further decreased insulin resistance." (PMID 35571083, 2022). "Hyperglycemia is induced via several mechanisms, among them enhanced insulin resistance, increased gluconeogenesis, and reduced insulin secretion by the pancreatic beta cells." (PMID 35725822, 2022).